MACC1 (MET transcriptional regulator MACC1)
Diseases named in the same sentence as MACC1 in open-access papers (continued):
Sharing a sentence is not in itself a finding about the gene and the disease.
cancer (continued). "In this study, it was uncovered that circ-PDE8A inhibits the function of miRNA-338, consequently escalating the levels of metastasis-associated in colon cancer 1 (MACC1), a target of miRNA-338." (PMID 32756339, 2020). "Compared with this result, although the information and relationship of carcinogenic risk factor exposure to MACC1 expression is limited, it seemed that the interaction and influence between MACC1 and risk factors varies in different cancers." (PMID 32047570, 2020). "Revealing studies have identified the association of MACC1 SNPs expression to clinical outcomes and cancer prognosis 22-26." (PMID 32047570, 2020). "The expression of the Metastasis associated in colon cancer 1 (MACC1) is often upregulated in many cancers." (PMID 31652539, 2019). "Some studies have suggested that MACC1 overexpression is significantly associated with unfavorable clinical outcomes in various cancers." (PMID 30515418, 2018). "Recent studies have shown that overexpression of metastasis-associated in colon cancer 1 (MACC1) is significantly associated with adverse prognoses of patients with different kinds of cancer." (PMID 30515418, 2018). "Metastasis-associated in colon cancer 1 (MACC1) has been reported to be overexpressed in multiple cancers and promote proliferation, metastasis, cancer stem cell-like properties, and drug resistance of cancer cells." (PMID 30082743, 2018). "One such promising biomarker that emerged in the recent past is Metastasis-Associated in Colon Cancer 1 (MACC1)." (PMID 28570591, 2017). "Loss of regulation control at the transcriptional and post-transcriptional levels of MACC1 lead to its overexpression in numerous cancer entities, which causes cancer progression." (PMID 27462788, 2016). "Metastasis-associated in colon cancer-1 (MACC1) gene located at 7p21.1 was identified by a genome-wide search for a set of differently expressed genes in primary and metastatic colon cancer." (PMID 27542234, 2016). "Metastasis associated in colon cancer 1 (MACC1), a newly identified oncogene, has been associated with poor survival of cancer patients by multiple studies." (PMID 26090393, 2015). "Recently, we have discovered that metastasis-associated in colon cancer-1 (MACC1) participates in GC progression." (PMID 25945841, 2015). "In terms of mechanism, miR-338-3p directly targeted zinc finger E-box-binding protein 2 (ZEB2) and metastasis-associated in colon cancer-1 (MACC1)." (PMID 25945841, 2015). "As expected, the subgroup analysis for cancers in gastrointestinal tract also consistently (p < 0.01, I2 = 72%) identified high MACC1 expression as a risk factor for poor OS (HR = 1.62, 95% CI: 1.10–2.40)." (PMID 26090393, 2015). "The metastasis-associated in colon cancer 1 gene (MACC1) has been found to be associated with cancer development and progression." (PMID 23717574, 2013). "Overexpression of MACC1 associates with the progression of these carcinomas and prognosis of the patients with these carcinomas." (PMID 23573286, 2013). "The newly discovered metastasis-associated in colon cancer-1 (MACC1) gene is a key regulator of the HGF/MET pathway." (PMID 22251819, 2012). "In an earlier study the new gene metastasis associated in colon cancer 1 (MACC1) was identified by differential display RT-PCR." (PMID 22838389, 2012). "Metastasis-associated in colon cancer 1 (MACC1) is demonstrated to be up-regulated in several types of cancer, and can serve as biomarker for cancer invasion and metastasis." (PMID 21923915, 2011). "Interestingly, large amounts of various cytokines can be produced by cancer stem cells, which have already been linked to MACC1." (PMID 38611008, 2024). "According to epidemiological research, SNPs in MACC1 may increase a person’s risk of developing cancer." (PMID 36979146, 2023).
cancer (continued). "Furthermore, MACC1 has been recognized as a prognostic, predictive, and causative biomarker in more than 20 different cancer entities, including CRC, lung cancer, and gastric cancer making it a promising molecular target for solid cancers." (PMID 36674695, 2023). "Notably, in many instances, MACC1 expression was additionally linked to increased metastasis formation, being the main reason for cancer mortality." (PMID 37051546, 2023). "MACC1 and cancer immunology have been linked in numerous studies." (PMID 36979146, 2023). "We hypothesized, that Metastasis-associated in colorectal cancer-1 (MACC1) induces a secretory phenotype to enforce metastasis in a paracrine manner, and found, that the cell-free culture medium of MACC1-expressing CRC cells induces migration." (PMID 36008464, 2022). "Moreover, besides inducing metastasis formation, MACC1 expression is also associated with increased resistance to standard and targeted therapeutics in several cancer types, including CRC." (PMID 32391276, 2020). "The objectives of this study were to define the associations among single nucleotide polymorphisms (SNPs) of metastasis-associated in colon cancer-1 (MACC1) gene, development and clinicopathological characteristics of uterine cervical cancer, and patient survival in Taiwan." (PMID 32174779, 2020). "The MACC1 expression or its functions may be altered by its single nucleotide polymorphisms (SNPs), which consequently influence the progression of cancer development." (PMID 32047570, 2020). "This may be caused by the different samples used for MACC1 detection, the methodology with different ELISA Kit, and more importantly, the different cancer types analysed." (PMID 30370603, 2019). "Metastasis associated in colon cancer 1 (MACC1) is upregulated in several types of cancer." (PMID 29966369, 2018). "In addition, a previous study reported that the expression of MACC1 is associated with the invasion and metastasis of various human cancers." (PMID 26043756, 2015). "However, the precise mechanisms by which the knockdown of MACC1 causes cancer cell cycle arrest and apoptosis requires further elucidation." (PMID 26043756, 2015). "In several cancer cell types, it is associated with the downregulation of common epithelial genes (cytokeratins, E-cadherin) and the upregulation of mesenchymal markers (vimentin, fibronectin, N-cadherin, and metastasis-associated in colon cancer-1 (MACC-1)) (Top)." (PMID 36612099, 2022). "The effect of MACC1 on promoting cancer progression and metastasis, as well as in reduced drug sensitivity has been reported in association with several cellular signaling pathways involved in carcinogenesis, but detailed molecular mechanisms of MACC1 in cancer progression are less well known." (PMID 33469705, 2021). "MACC1 also contributes to the promotion of mesenchymal epithelial transition, and cancer immunotherapy." (PMID 40354443, 2025). "Here, we report for the first time that the metastasis inducer MACC1 transcriptionally regulates LGR5 expression to promote cancer stem cell properties in CRC by using 2D and 3D cell culture models, CRC-PDX mouse models as well as human CRC patient samples." (PMID 38339354, 2024). "While MACC1 is already established as a marker of metastasis, we highlight here that it possesses additional value as a predictor for cancer immune evasion by manipulating immune cell infiltration and function." (PMID 38611008, 2024). "Since its first description in 2009, MACC1 has been recognized as a prognostic and predictive biomarker as well as a driver of metastasis formation in over 20 cancer entities." (PMID 38611008, 2024). "We previously showed an involvement of MACC1 in cancer stemness in the mouse intestine of our MACC1 transgenic mouse models." (PMID 38339354, 2024). "MACC-1 is a transcriptional regulator involved in various cancer-related processes, including cell proliferation, migration, and invasion." (PMID 39273182, 2024).
cancer (continued). "We compared expression differences of traditional cancer stem biomarker Sox2, Nanog and MACC1 between the two cultured conditions." (PMID 39695175, 2024). "Most notably, HGF stimulation can induce the expression of PD-L1 through c-MET and thereby contribute to cancer cell immune evasion, a process likely dependent on MACC1 as a core regulator/effector of this signaling pathway." (PMID 38611008, 2024). "Further evidence is provided by the general use of statins, potent transcriptional inhibitors of MACC1 expression, as they are widely used and are often also prescribed to patients treated for cancer." (PMID 38611008, 2024). "In this context, MACC1 has been identified to regulate the cancer cell stemness properties through the induction of transcription factors known as core regulators of multipotency such as octamer-binding transcription factor 4 (Oct4) and Nanog." (PMID 38611008, 2024). "Proteins up-regulated by LPA included metastasis-associated in colon cancer protein 1 (MACC1) and thrombospondin-1 (TSP1/THBS1); both MACC1 and TSP1 regulated cancer cell adhesion and motility." (PMID 38396744, 2024). "Metastasis-associated in colon cancer 1 (MACC1) is a protein involved in the pathogenesis of CRC, as it has been associated with aggressive cancer cell behavior, enhanced metastatic potential, and reduced overall survival in patients." (PMID 39273182, 2024). "Taken together, MACC1 promotes cancer stem cell-like properties in CRC via employment of LGR5 as a novel signaling mediator." (PMID 38339354, 2024). "c-MET and SPON2, as transcriptional targets of MACC1, induced metastasis in xenograft and genetically modified mouse models, and is closely related to the metastasis of cancer patients." (PMID 39695175, 2024). "In this study, we will explore the potential role and mechanism of MACC1 on the dedifferentiation of non-cancer stem cells." (PMID 39695175, 2024). "FGD5-AS1 and MACC1 are highly expressed in cancer tissues and radiation-resistant cell lines, and they improve cancer cell radiation resistance." (PMID 36979146, 2023). "MACC1 has been found to play key roles in cancer cell migration, invasion, epithelial-to-mesenchymal transition, and metastasis in various types of cancer, through activation of MET signaling." (PMID 37496665, 2023). "MACC1 levels in the primary tumors or patient blood were significantly higher in cancers that metachronously developed distant metastases compared to those which did not metastasize." (PMID 38144523, 2023). "MACC1 is a master oncogene involved in multiple aspects of cancer metastasis in a broad variety of tumors." (PMID 37664587, 2023). "Poor prognostic factors include big tumors, grade III tumors, positive lymph node metastases, lymphovascular invasion, and stage III cancers, and elevated Ki-67 expression was substantially related with high MACC1 expression." (PMID 36979146, 2023). "The unique structural characteristics of MACC1 help us better understand its mechanism of action in cancer." (PMID 36979146, 2023). "MACC1’s biological role, molecular mechanism, and pathway are important for understanding cancer progression." (PMID 36979146, 2023). "The impact of the natural compound cantharidin and norcantharidin on S100A4 and MACC1 gene expression, cancer cell migration, motility, and colony formation in vitro was tested." (PMID 36674695, 2023). "The biological role of MACC1 in malignant tumors is related to the state of the Akt signaling pathway." (PMID 36979146, 2023). "Previous publications already report the transcriptional regulation of cancer- and metastasis-related genes by MACC1 in CRC, like the hepatocyte growth factor receptor c-MET, the adhesion factor SPON2 and the stem-cell transcription factor NANOG." (PMID 35597866, 2022). "Metastasis-Associated in Colon Cancer 1 (MACC1) is a strong prognostic biomarker inducing proliferation, migration, invasiveness, and metastasis of cancer cells." (PMID 35406521, 2022).
cancer (continued). "The present study analyzed the expression levels and evaluated the prognostic value of MACC1 in multiple types of human cancers finding that MACC1 was over-expressed in COAD, with this increased expression predictive poor clinical features and poor prognosis." (PMID 36545127, 2022). "The prognostic value of MACC1 expression in patients with 33 types of human cancers from the TCGA database was analyzed." (PMID 36545127, 2022). "The present study analyzed the expression of MACC1 in 33 types of cancer using data from the TCGA and GTEx databases and found that MACC1 mRNA was more highly expressed in COAD than in corresponding normal colon tissues." (PMID 36545127, 2022). "The CC manipulations led to differential expression of several key EMT genes, among them MACC1, and affected cancer proliferation and migration." (PMID 35884519, 2022). "The metastasis inducing gene MACC1 is a prognostic and predictive biomarker for metastasis in several cancers." (PMID 35597866, 2022). "Next, by using the TCGA colon and rectum adenocarcinoma (COAD-READ) cohorts, we have refined the context of MACC1 expression with CRC molecular subtypes and the association with cancer patients’ clinical outcomes." (PMID 35406521, 2022). "Altogether, these data point to a potential interaction between MACC1 and the circadian clock network, which contributes to altered clock phenotype and cancer progression, possibly via core-clock components." (PMID 35884519, 2022). "In this study, we analyzed the expression level and prognostic value of MACC1, as well as their correlation, in patients with various types of cancer included in The Cancer Genome Atlas (TCGA) and Genotype-Tissue Expression (GTEx) databases." (PMID 36545127, 2022). "Since both markers have been reported individually as stage-independent prognostic biomarkers across multiple cancer entities, we assessed the combined prognostic value of MACC1 and S100A4 for MFS and OS." (PMID 36008464, 2022). "To further assess the potential role of the CC on cancer metastasis, we focused on MACC1 that showed the most striking expression change upon the KOs." (PMID 35884519, 2022). "The proteins that promote the proliferation and migration of cancer cells in the MACC1 OE cancer tissues were significantly higher than those in the vector group (P < 0.01)." (PMID 35874635, 2022). "This study is, to our knowledge, the first identification of the effect of curcumin on the restriction of cancer motility, proliferation, and colony-forming ability by using MACC1 as a target." (PMID 36432477, 2022). "We discovered that through β-catenin signaling, MACC1 directly induces S100A4 expression and secretion, and further mediates MACC1 pro-migratory effect on cancer cells through S100A4 as the enforcing molecule." (PMID 36008464, 2022). "The role of MACC1 in cancer cells was demonstrated by overexpression and silencing of MACC1 in gain or loss function experiments." (PMID 35874635, 2022). "We generated CC manipulated CRC cells (ARNTL, PER2 or NR1D1 knockout or knockdown) and compared clock (ARNTL-promoter activity) and cancer phenotype (proliferation, apoptosis and invasion) to that of MACC1 manipulated (knockout or overexpression) cells." (PMID 35884519, 2022). "The results of the current study point to a strong interplay between cancer cell properties (e.g., proliferation and invasion) and the circadian clock via MACC1 in CRC." (PMID 35884519, 2022). "Taken together, these results suggested that the potential prognostic value of MACC1 mRNAs differs among different types of cancer." (PMID 36545127, 2022). "High expression levels of MACC1 promote cell proliferation, motility and drug resistance, thereby facilitating cancer progression and metastasis." (PMID 35597866, 2022). "In summary, the findings of this study demonstrated that MACC1 is a novel and potent regulator of cancer metabolism exerting multiple effects on metabolic rewiring." (PMID 33652667, 2021).
cancer (continued). "Although many reports clarified the importance of PTMs, such as glycosylation, phosphorylation, ubiquitination, methylation, and so on, for inflammation or cancer, it still needs more studies on the PTMs of MACC1." (PMID 34072650, 2021). "Subsequent prognostic assessment demonstrated the validity of MACC1/SPINT1 panel in predicting patient survival among different groups with eight cancer types." (PMID 33751856, 2021). "Therefore, MACC1 SNP rs4721888 might have some effect on cancer incidence or susceptibility." (PMID 34072650, 2021). "Kaplan‐Meier plots and receiver operating characteristics analysis revealed that the two‐gene signature combining MACC1 with SPINT1 was effective in predicting survival in all eight cancer cohorts tested." (PMID 33751856, 2021). "It was without exception that the AUCs for OS and DFS for the signature in the eight cancers were elevated, compared with those for MACC1 or SPINT1 separately, indicating that the MACC1/SPINT1 signature was an effectively prognostic model in these cancers." (PMID 33751856, 2021). "Here, we performed a bioinformatics and molecular analyses of clinical samples for the identification of a MACC1/SPINT1 panel as a pan‐cancer prognostic tool." (PMID 33751856, 2021). "Here we report, that MACC1, a causal and prognostic marker for CRC metastasis, is involved in the regulation of cancer-related growth factor signaling." (PMID 33469705, 2021). "With ABCB1 as such a target gene, the overexpression of MACC1 in cells with activated Wnt/β-catenin signaling leads to increased resistance to anti-cancer therapies, including anthracyclines like doxorubicin." (PMID 32391276, 2020). "The presence of MACC1 on promoters regulating cancer progression and metastasis has previously been reported." (PMID 32391276, 2020). "Since TNF-α triggers MACC1 expression, we were interested in identifying the responsible receptor mediating this effect in cancer cells." (PMID 32670264, 2020). "It has also been reported that overexpression of MACC1 was connected with poor prognosis in diverse of cancers." (PMID 32595704, 2020). "This is the first identification of saffron-based compounds restricting cancer cell proliferation and motility via the novel target MACC1." (PMID 32756469, 2020). "Increased expression of MACC1 leads to greater proliferation, induction of angiogenesis, and is antiapoptotic in various cancers." (PMID 33680922, 2020). "The second candidate, MACC1 was involved in epithelial–mesenchymal transition and was potent regulator of cancer metastasis and cell invasion." (PMID 33680922, 2020). "This research is the first identification of saffron-based compounds restricting cancer cell proliferation and motility progression via the novel target MACC1." (PMID 32756469, 2020). "Several studies have indicated that MACC1 has potential as a prognostic marker for cancer progression." (PMID 33425885, 2020). "Mechanisms of MACC1 in cancer development and progression have been reported in in vitro cell model and pre-clinical murine models." (PMID 30805302, 2019). "Circulating MACC1 transcripts are established as prognostic plasma marker for several cancer entities." (PMID 31200581, 2019). "Circulating MACC1 transcripts have been found in the peripheral blood of cancer patients and have been established as prognostic plasma marker for several solid cancer entities." (PMID 31200581, 2019). "Another potential therapeutic is the chimeric antibody Chanti-MACC1, which targets MACC1 directly and inhibits proliferation, migration, and invasion of cancer cells." (PMID 31200581, 2019). "Data revealed that, in addition to subtypes of cancer and patient age, MACC1 index (media n = 0.950) is an independent prognostic factor for CRC patients (HR = 1.533, p = 0.005)." (PMID 30805302, 2019). "During cancer progression, MACC1 overexpression should inhibit cancer cell apoptosis and promote cancer cell EMT via HGF/MET pathways." (PMID 30021598, 2018).